L1CAM (L1 cell adhesion molecule)
Diseases named in the same sentence as L1CAM in open-access papers (continued):
Sharing a sentence is not in itself a finding about the gene and the disease.
Hydrocephalus (continued). "The most common form of hydrocephalus is X-linked hydrocephalus which is usually associated with stenosis of the aqueduct of Sylvius, and the gene responsible for this disease (L1CAM) was identified." (PMID 19924295, 2009). "In conclusion, this study underscores the critical role of advanced computational tools, such as AlphaMissense and AlphaFold, in the identification and validation of pathogenic variants, particularly in families with a history of hydrocephalus linked to the L1CAM gene." (PMID 41423712, 2025). "Neurological diseases such as hydrocephalus have been linked to mutations in L1CAM." (PMID 39273702, 2024). "L1CAM-associated hydrocephalus is the most common heritable form of ventriculomegaly." (PMID 37493877, 2023). "This neuropathological feature was highly suggestive of MPDZ variations which have been associated with non-syndromic hydrocephalus due to Sylvius Aqueduct atresia, distinguishing them from cases with L1CAM variations, in which hydrocephalus was associated with Sylvius Aqueduct stenosis." (PMID 36803301, 2023). "In this study, a L1CAM gene exonic missense variant (c.1108G > A, p.G370R) was identified in two induced fetuses (abnormal fetuses), who presented corpus callosum agenesis accompanied with hydrocephalus." (PMID 34914080, 2022). "Here, a L1CAM gene exonic missense variant (c.1108G > A, p.G370R) was identified in two induced fetuses (abnormal fetuses), who presented corpus callosum agenesis accompanied with hydrocephalus." (PMID 34914080, 2022). "Four genes were found to be involved in four cases each: the RAPSN gene related to fetal akinesia syndrome II, the SLC26A3 gene related to congenital chloride diarrhea, the L1CAM gene related to hydrocephalus with X-linked inherence, and the FOXC2 gene related to lymphedema-distichiasis syndrome." (PMID 34682862, 2021). "For instance, familial recurrence from the maternal side may suggest X-linked hydrocephalus (MIM# 307000), the most common heritable form of hydrocephalus, due to mutations in L1CAM, encoding the L1 cell adhesion molecule." (PMID 35096710, 2021). "Variants in L1CAM are well known to cause X-linked isolated and syndromic hydrocephalus." (PMID 30679815, 2019). "In addition, Ccdc39prh/prh mutants with L1 cell adhesion molecule (L1cam) gene mutation, which causes X-linked human congenital hydrocephalus, showed an accelerated early hydrocephalus phenotype (P<0.05-0.01)." (PMID 31771992, 2019). "Our study first indicated c.453G > T (p.Gly151 = ) in L1CAM could be disease causing for hydrocephalus, which would aid in genetic counseling for the prenatal diagnosis of hydrocephalus." (PMID 31572438, 2019). "In patients with isolated hydrocephalus, L1CAM mutations represent the most common aetiology." (PMID 28460636, 2017). "Interestingly, L1cam‐deficient mice also develop postnatal hydrocephalus, while in humans carrying LCAM1 mutations hydrocephalus often develops already before birth." (PMID 28500065, 2017). "Genetic causes related to specific human hydrocephaly phenotypes are still relatively unknown, with the notable exception of L1-CAM mutations, involved in a syndrome including hydrocephalus due to aqueductal stenosis." (PMID 25729350, 2015). "The L1-6D mutant mice, which are homozygous for a deletion that removes the Ig6 domain of L1CAM, revealed typical hydrocephalus." (PMID 40520226, 2025). "Both of these causes can lead to enlarged ventricles in patients with HSP, for example, SPG1/L1CAM has enlarged ventricles due to hydrocephalus." (PMID 39932116, 2025). "In mice, widely used models include SUMS/NP, hydrocephalus-1 (hy-1), hydrocephalus-2 (hy-2), hydrocephalus-3 (hy-3) and L1CAM mutants." (PMID 39908266, 2025). "This study emphasizes the importance of ultrasonic manifestation and family history of fetal hydrocephalus for L1CAM diagnosis." (PMID 35571029, 2022).
Hydrocephalus (continued). "The findings of this study suggest a potential possibility of L1CAM gene screening for prenatal diagnoses for fetuses presented corpus callosum agenesis accompanied with hydrocephalus." (PMID 34914080, 2022). "Our study expands the genotypes of L1CAM and aids the genetic counseling of fetal hydrocephalus and even preimplantation genetic testing for the monogenic disorder." (PMID 35571029, 2022). "Our data indicated that the detection rate of L1CAM gene mutant was 3% (1/35) in isolated fetuses prenatally suspected of corpus callosum agenesis accompanied with hydrocephalus, using Sanger sequencing to detect 29 exons and intron/exon boundaries." (PMID 34914080, 2022). "By only detecting 29 exons and intron/exon boundaries using Sanger sequencing, our data indicated that the detection rate of L1CAM gene mutant was 3% (1/35) in isolated fetuses prenatally suspected of corpus callosum agenesis accompanied with hydrocephalus." (PMID 34914080, 2022). "In human, L1-CAM LOF mutations cause X-linked hydrocephalus (OMIM #307000), and deficiency of this gene in Xenopus and mice also causes hydrocephalus." (PMID 32902807, 2021). "For example, L1CAM gene, well known in hydrocephalus research, is in chromosome X of humans and mice." (PMID 34064609, 2021). "Here, we studied the genetic interaction of two hydrocephalus-related genes, L1cam and Ccdc39, through genetic, survival and growth characterization of the Ccdc39prh/prh mutant rat in the presence and absence of an L1cam-null allele." (PMID 31771992, 2019). "The earliest monogenic link of hydrocephalus had been made to L1CAM, which encodes the L1 neuronal cell adhesion molecule." (PMID 30518636, 2019). "L1CAM mutations can also lead to syndromic disorders (L1 syndrome, CRASH syndrome) associated with hydrocephalus." (PMID 28500065, 2017). "If abnormal positioning of the fetal thumbs is detected in a fetus with severe hydrocephaly, these pregnancies should be eligible for prenatal molecular testing in order to determine the integrity of the L1CAM gene." (PMID 26078893, 2015). "Interactions between L1cam and the ciliary morphology-related gene Ccdc39 were explored, with L1camy/- mutants in combination with Ccdc39prh/prh double mutants displaying more severe hydrocephalus, accelerating neonatal hydrocephalus development." (PMID 39908266, 2025). "L1CAM mice harbor stenosis of the aqueduct of Sylvius between the 3rd and 4th ventricles, but it was judged to be a result of the increased intraventricular pressure and the ensuing compression of the aqueduct's walls, rather than the cause of hydrocephalus." (PMID 30518636, 2019). "In individuals with apparently isolated hydrocephalus or with no major additional clinical findings, L1CAM mutations represent the most common genetic form with a prevalence of approximately 1:30,000 and account for about 5–10% of males with non-syndromic congenital hydrocephalus." (PMID 28460636, 2017). "If hydrocephalus is found on brain MRI and acquired causes are ruled out, a careful neuroradiological assessment may identify neuroradiological features, possibly suggesting a specific genetic etiology, such as aqueductal stenosis due to L1CAM mutations." (PMID 35096710, 2021). "The brain malformations typical to the L1 syndrome were attributed to the inter‐neuronal adhesion function of L1CAM, but no mechanism had been invoked to account specifically for the formation of hydrocephalus." (PMID 30518636, 2019). "Finally, the neuroepithelial cells of the ventricular zone and the ependymal lining of the ventricular wall rely on cell adhesion molecules such as L1CAM and NCAM for structural integrity, and ventricular zone junctional proteins are known to be impaired in hydrocephalus." (PMID 28212403, 2017).
neuroblastoma (42 papers, 2010 to 2025). Neuroblastoma (NB) is the most common solid, extracranial childhood tumor. "Radio- or chemoresistance is associated by treatment-induced upregulation of L1CAM in neuroblastoma and pancreatic cancer." (PMID 31455004, 2019). "Regardless of these contradictions, active development of various therapeutic approaches using the L1CAM molecule as a diagnostic and therapeutic marker for the treatment of neuroblastoma is underway." (PMID 30116755, 2018). "Using conditioned media from neuroblastoma cells expressing α-synuclein mutants or patient-derived induced pluripotent stem cell (iPSC) neurons with α-synuclein gene triplication, we found that association of α-synuclein with the L1CAM+ EV surface is increased under pathological conditions." (PMID 40056910, 2025). "Here we aimed to gain insights into the cell interactions and signaling pathways that assist migration into and through the tumor using our 3D bioprinted neuroblastoma model and L1CAM-CAR T or untransduced T cells as a simplified system." (PMID 41394860, 2025). "Overall, these data support B7-H3 and L1CAM as subtype-independent neuroblastoma immunotherapeutic targets." (PMID 39825754, 2025). "CAR T cell therapies targeting antigens on neuroblastoma cells, such as L1CAM, or GD2 have been explored." (PMID 41366257, 2025). "Analyzing ImmunoTar’s results in the PDX surfaceome data showed that L1 cell adhesion molecule (L1CAM) was ranked as the top candidate in neuroblastoma, which is to be expected since it was utilized in the optimization algorithm as a known-positive target." (PMID 39932005, 2025). "CAR-T cells against L1CAM developed from cells directly isolated from 4 neuroblastoma patients have shown anti-tumour reactivity in vitro and in immunocompromised mice." (PMID 39489087, 2024). "A clinical trial was undertaken several years ago in patients with neuroblastoma who received one or more infusions of L1CAM-retargeted CAR T-cell clones." (PMID 36829563, 2023). "In the current study, we demonstrate that genome editing events occurring in L1CAM, an X-chromosome gene encoding a cell surface protein, can be readily monitored using flow cytometry (FCM) in multiple human cell lines including neuroblastoma cell lines." (PMID 37943774, 2023). "L1CAM (CD171), for example, is expressed in a supposedly glycosylated form by neuroblastoma, and an antibody recognizing this glycosylation-dependent epitope can be used for the generation of a CAR-product." (PMID 36077730, 2022). "Fittingly, other studies already revealed that radio‐ or chemotherapy resistance is induced by upregulation of L1CAM in neuroblastoma and pancreatic cancer." (PMID 34228897, 2022). "The other two neuroblastoma cell lines, with the lower levels of L1CAM target expression, exhibited only very low FAS levels on the cell surface that were only slightly upregulated by IFNG treatment regardless of concentration." (PMID 34771652, 2021). "Children suffering from primary refractory or relapsed neuroblastoma were treated with L1CAM-targeting CAR T cells in an ongoing clinical phase I trial (NCT02311621, https: clinicaltrials.gov, accessed on 27 September 2021)." (PMID 34771652, 2021). "Our results show that cytotoxicity induced by L1CAM-specific CAR T cells was significantly increased by SP-2509 pretreatment of neuroblastoma cells." (PMID 34771652, 2021). "Recently, children suffering from refractory neuroblastoma were treated with L1CAM-targeting CAR T cells in a clinical phase I trial (NCT02311621, https:clinicaltrials.gov)." (PMID 34267756, 2021).
neuroblastoma (continued). "L1CAM-specific CAR T cells were able to recognize and infiltrate our bioprinted 3D neuroblastoma models, with microscopic assessment verifying deep L1CAM-specific CAR T cell infiltration." (PMID 34267756, 2021). "Treating patient-derived neuroblastoma xenografts with human L1CAM-targeting CAR T cells confirmed the superiority of CD28 co-stimulus." (PMID 33801448, 2021). "For combination experiments, the three neuroblastoma cell lines were exposed to fresh medium or pretreated for 72 h with 0.5 μM SP-2509 before exposure to L1CAM-specific CAR T cells in vitro." (PMID 34771652, 2021). "Using monoclonal, murine-derived L1CAM-specific CAR T cells in Rag-/- mice harboring established xenografted tumors from a human neuroblastoma cell line revealed a clear superiority in CAR T cell trafficking using CD28 co-stimulation." (PMID 33801448, 2021). "L1CAM-specific CAR T cell activation by neuroblastoma cells was stronger in the 3D model than in 2D cocultures, but neuroblastoma cell lysis was lower." (PMID 34267756, 2021). "Recently, children diagnosed with refractory neuroblastoma were treated with L1CAM-targeting CAR T cells harboring the 4-1BB co-stimulatory domain in a clinical phase I trial (NCT02311621, Available online: https:clinicaltrials.gov (accessed on 1 March 2021))." (PMID 33801448, 2021). "We developed a novel method to analyze CAR T cell effector function in a stereolithographically bioprinted 3D tumor model, and present proof-of-concept here using CAR T cells targeting one neuroblastoma target protein, L1CAM, and a neuroblastoma cell line." (PMID 34267756, 2021). "Here, we demonstrate that murine T cells equipped with L1CAM-specific CAR constructs harboring human-derived signaling domains efficiently produce cytokines after encounter of L1CAM antigen on human neuroblastoma cells." (PMID 33801448, 2021). "For a clinically relevant setting, we chose a neuroblastoma PDX mouse model with high L1CAM expression on the tumor cells." (PMID 33801448, 2021). "Taken together, CD28 co-stimulus was superior for inducing regression of established neuroblastoma xenografts by L1CAM-specific mouse CAR T cells, predominantly those harboring the short spacer domain." (PMID 33801448, 2021). "L1CAM is overexpressed on neuroblastomas and many other pediatric and adult solid tumors with limited normal tissue expression, and a relatively tumor-restricted CE7 epitope of L1CAM has been the recent focus of targeting with CAR T cells." (PMID 34113750, 2020). "L1CAM is also highly expressed in the pediatric cancer Neuroblastoma where it is being targeted via CAR T cell-based approaches." (PMID 33196691, 2020). "Targeting of L1CAM(CD171) with CART cells in neuroblastoma has also provided important lessons on the tumor-normal tissue expression threshold." (PMID 34113750, 2020). "This binding has synergistic effects on L1CAM-mediated cell aggregation and adhesion in neuroblastoma cells." (PMID 32429448, 2020). "L1CAM is additionally highly expressed in Neuroblastoma, the most common extracranial solid malignant neoplasm of childhood, where it is being targeted via CAR T-cell approaches." (PMID 33196691, 2020). "CE7R-modified cytotoxic T cells are redirected to L1CAM-positive human neuroblastoma cells and activated for tumor cell lysis and TC-1 cytokine production." (PMID 30116755, 2018). "Despite preclinical development of CAR T cells against a variety of neuroblastoma associated antigens, only those directed against GD2 and L1-CAM (CD171) have reached clinical trials." (PMID 30459759, 2018). "Another target of interest in neuroblastoma is L1-CAM, an adhesion molecule that is overexpressed on neuroblastoma." (PMID 30459759, 2018). "Still, most authors who conducted large-scale studies of L1CAM expression in tumors of various origin, including neuroblastoma, concur that expression of this marker is rather a prognostic factor of poor outcome." (PMID 30116755, 2018).
neuroblastoma (continued). "So far, the only clinical application of L1CAM in patients consisted in the use of a radioactively labeled antibody as an imaging tool to detect neuroblastoma, a study that pointed to L1CAM as a suitable target for radioimmunotherapy of that tumor type." (PMID 28134764, 2017). "Conversely, Wachowiak and colleagues reported that the expression of L1CAM exhibited a favourable prognostic effect in children with neuroblastoma." (PMID 27833079, 2016). "CAR T cells targeting diasialoganglioside (GD2) antigen and L1-cell adhesion molecule (L1CAM) were generated for treatment of neuroblastoma." (PMID 23829929, 2013). "We hypothesize that the phenomena of immune escape will be less likely when targeting pan-neuroblastoma cell surface proteins such as B7-H3 and L1CAM, and/or dual targeting strategies that consider both the ADRN and MES cell states." (PMID 39825754, 2025). "Cytotoxicity against SK-N-BE neuroblastoma cells (challenged 24h in coculture) was comparable between L1CAM-CAR T cells with and without SELPLG deficiency." (PMID 41394860, 2025). "Similar to our findings, in a previous study, L1CAM knockdown radiosensitized neuroblastoma cells by simultaneous downregulation of proto-oncogene myelocytomatosis neuroblastoma MycN and the upregulation of tumor suppressor PTEN, which inhibits PI3K/AKT/mTORC1 signaling." (PMID 40429728, 2025). "In addition, we disrupted L1CAM in three more neuroblastoma cell lines derived from male patients (CHP-134, LA-N-5, and TGW) that robustly express L1CAM." (PMID 37943774, 2023). "Here, we test whether CD8+ L1CAM-specific CAR T cell infiltration can be assessed using a bioprinted 3D neuroblastoma model, in which the embedded neuroblastoma cells express the target antigen, L1CAM." (PMID 34267756, 2021). "We used established neuroblastoma cell lines with high, low, or heterogeneous antigen expression, and showed that the in vitro efficacy of L1CAM-directed CAR T cells was significantly reduced when the tumor antigen was less strongly or heterogeneously expressed on tumor cells." (PMID 34771652, 2021). "The L1 cell adhesion molecule was discovered on neuroblastoma cells in the 1980s." (PMID 30116755, 2018). "It has been shown in the neuroblastoma cell line IMR-32 that the knockdown of L1CAM leads to a decrease in the formation of tumorospheres, a decrease in the proliferation and migration of tumor cells, and downregulation of MYCN and upregulation of the PTEN tumor suppressor." (PMID 30116755, 2018). "Similar to GD2, L1 cell adhesion molecule (L1-CAM) is also overexpressed in neuroblastoma." (PMID 28356156, 2017). "In addition, the predictive role of L1CAM in the prognoses of neuroblastoma, gallbladder cancer, renal cell cancer, gastrointestinal stromal tumours and several additional tumours is controversial, and some studies did not consistently show significance." (PMID 27833079, 2016). "This conclusion is reinforced by the observation that in neuroblastomas, which are tumors of neural nature, expression of L1CAM was found associated not with severity, but with favorable outcomes." (PMID 22973895, 2013). "Protein abundance of KCNH1 was comparable to targets under development in neuroblastoma including NCAM1, L1CAM and CD276, and higher than other known immunotherapeutic targets such as ALK and GPC2." (PMID 38895237, 2024). "Consistent with this expression pattern, we found that four neuroblastoma cell lines and a colon cancer cell line, HCT116, exhibit high L1CAM expression levels." (PMID 37943774, 2023). "FAS upregulation sensitized neuroblastoma cells to FAS-FASL-dependent killing and augmented L1CAM-directed CAR T cell therapy against antigen-poor or even antigen-negative tumor cells in vitro." (PMID 34771652, 2021). "We flow cytometrically analyzed expression of the L1CAM and GD2 surface antigens on neuroblastoma cells as well as CD3+ and CD8+ surface molecules on L1CAM-specific CAR T cells and untransduced T cells after enzymatic digestion." (PMID 34267756, 2021).